CCR8 (C-C motif chemokine receptor 8)
Diseases named in the same sentence as CCR8 in open-access papers (continued):
Sharing a sentence is not in itself a finding about the gene and the disease.
cancer (continued). "Chemokines (CCR1, CCR2, CCR3, CCR4, CCR5, CCR6, CCR7, and CCR8) and receptor genes (CXCL1-17, CCL1-14, CCL16-26) were positively associated with necroptosis levels in various cancers." (PMID 36170029, 2022). "On the basis of the results from these three approaches, we concluded that CCR8+ Tregs strongly suppressed CD8 T cell effector functions for cancer immunity." (PMID 35354899, 2022). "As suggested by the recent data from several mouse cancer models, CCR8 represents a promising target for cancer immunotherapy." (PMID 35158783, 2022). "Simultaneously, we found that the expression of FASN was correlated with various chemokines (e.g., XCL2 and CCL14) and chemokine receptors (e.g., XCR1 and CCR8) in different cancers." (PMID 36555243, 2022). "Several CCR8-targeted drugs are currently in development, and we are also planning a clinical study of anti-human CCR8 antibody for human cancer." (PMID 35354899, 2022). "This review focuses on CCR8, a chemokine receptor highly expressed on suppressive immune cells, and its potential value as a novel target in cancer therapy." (PMID 35158783, 2022). "TGF-β-induced EMT can upregulate chemokine receptors, including CXCR4, CXCR5, CCR7 and CCR8 in cancer cells, thus enabling them to follow chemotactic gradients to lymphatic vessels." (PMID 33808959, 2021). "The finding that CCR8 upregulation can be detected on effector ti-Tregs of multiple human cancer types by both this study and previous studies supports a broad applicability of CCR8+ cell-depleting therapeutics in the clinic." (PMID 33589525, 2021). "This chemokine causes cancer cell migration and EMT by activating its receptors, phosphatidylinositol transfer protein 3 (PITPNM3) and CCR8." (PMID 33076281, 2020). "These outcomes favor additional clinical assessment of CCR8 reduction along with immune checkpoint inhibitors as a new cancer immunotherapy." (PMID 33519807, 2020). "Metastasis to lymph nodes is not only associated with the described mechanism but also with the high expression of CCL1 in a lymph node combined with the expression of CCR8 on a cancer cell." (PMID 33076281, 2020). "Even more promising are anti-CCR8 therapies, with the potential to transform cancer immunotherapy." (PMID 41368133, 2025). "Anti-CCR8 antibodies are currently undergoing clinical trials for the treatment of cancer." (PMID 41323783, 2025). "One factor that might be worth looking into is Prostaglandin E2, considering its potential to be generated by cancer cells and its documented ability to upregulate CCR8 in both naive and effector T cells." (PMID 38231448, 2024). "However, to our knowledge, our data in this study provide the first evidence suggesting that CCR8+ Tregs can suppress CD8+ T cell cytotoxic activity in vivo within the TME of human cancer patients." (PMID 38783281, 2024). "Consequently, the development of therapeutic antibodies targeting CCR8 has been pursued as a potential approach for cancer treatment." (PMID 38231448, 2024). "These preclinical findings suggest that targeting CCR8 may be a promising approach for the treatment of cancer." (PMID 36765704, 2023). "Additionally, the mRNA levels of Treg chemokine receptors Ccr4, Ccr8, and Ccr10 as well as their ligands, Ccl1, Ccl17, and Ccl22 are significantly upregulated in the v-rasHa/ΔNp63α carcinomas compared to v-rasHa/Stuffer tumors or normal skin." (PMID 37638000, 2023). "In fact, the selectivity of CCR8 for intratumoral Treg cells is remarkable and warrants a more detailed discussion about potential safety concerns vis-à-vis approved antibody-based drugs that are widely used in current cancer therapies." (PMID 35158783, 2022). "Future cancer-targeted therapies may benefit from a more detailed understanding of the involvement of CCR8 and its ligands in immunological processes." (PMID 35158783, 2022). "SCS LECs produce CCL1 and chemoattract cancer cells expressing CCR8 to lymph nodes." (PMID 33808959, 2021).
cancer (continued). "Along with this, recently it has been reported that anti-CCR8 mAb could be used to limit cancer growth in several cancer models." (PMID 34944943, 2021). "Inhibiting CCR8 arrests cancer cells in afferent lymphatic vessels." (PMID 33808959, 2021). "Interestingly, low protein expression levels of CCR6 and CCR8 were found in cancer tissues and adjacent tissues." (PMID 32641093, 2020). "Recently, chemokine receptor named CCR8 (a receptor for CCL1) has been discovered which is expressed on intratumoral Tregs in several cancers, notably breast, colon, lung, and renal cell carcinoma with low expression in Th2 and monocytes with small proportions of expression in Th2 and monocytes." (PMID 33519807, 2020). "Previous studies have shown that activated Treg in cancer express the CCR8 marker." (PMID 31991588, 2020). "In addition to the effect on a cancer cell, CCL1 causes angiogenesis on vascular endothelial cells via CCR8." (PMID 33076281, 2020). "In glioblastoma, a distinct EV uptake mechanism was recently uncovered, which involves a triple interaction between the chemokine receptor CCR8 on cancer cells, glycans exposed on EVs and the soluble ligand CCL18 as a bridging molecule connecting EVs to cancer cells." (PMID 30925927, 2019). "Chemokine (C-C motif) receptor 8 (CCR8) could drive cancer progress through recruiting certain immune cells." (PMID 26716905, 2016). "Besides, the presence of CCL4 in NK cells, along with its receptor SLC7A1 in cancer cells, and CCR8 in CD4 + naïve T cells/Treg cells signified an activation of NK cells, which may predict a more favorable pathological response in pCR patients before NAT." (PMID 38566201, 2024). "Our results, in striking contrast to the anti-CCR8 ADCC strategy, pave the way for a safer and more effective treatment of HCC and other cancers." (PMID 40186298, 2025). "In the radar plots analyzing correlations between gene expression and TMB and MSI, CCR8, CD274, and PDCD1 expression levels showed significant positive correlations with TMB and MSI in several cancer types." (PMID 39273290, 2024). "In our comprehensive analysis, we integrated multiple analytical methods to evaluate the potential effectiveness of CCR8 and immune checkpoint inhibitor (ICI) combination therapy across six selected cancer types." (PMID 39273290, 2024). "The accumulation of Tregs in tumors is chemokine-dependent and is mediated by the upregulated expression of C-C motif chemokine receptor 8 (CCR8), CCR4, CCR6 and IL-33 receptor (ST2) in multiple human cancers." (PMID 38891091, 2024). "Specifically, chemokines such as CXCL9, CXCL10, and CXCL11 and chemokine receptors such as CXCR5, CCR4, CCR8, and CCR1 were positively correlated with IGF2BP3 expression in various cancer types." (PMID 36761737, 2023). "The data revealed that cancer areas had higher PGE2 and the combination of the active form of VitD and PGE2 induced CCR8 in T cells and reduced cytokine production." (PMID 34025655, 2021). "We then analyzed the direct effect of the TME by exposing T cell subsets to cancer secretomes and observed the OSCC secretome induced CCR8 expression and reduced cytokine production from both subsets." (PMID 34025655, 2021). "Apart from NIR1, CCR8 and CCR6 have also been validated as CCL18 receptors in existing cancer research." (PMID 32641093, 2020). "In cancer, CCL1 has an antiapoptotic activity and induces chemoresistance to anticancer drugs due to the activation of the ERK MAPK cascade via CCR8." (PMID 33076281, 2020). "Our study paves the way for the clinical study of CCR8 antagonists in HCC and other cancers." (PMID 40186298, 2025). "Our study paves the way for the clinical study of CCR8 antagonist in HCC and other cancers." (PMID 40186298, 2025). "Since TCM has soluble factors produced by cancer cell lines, we hypothesized that TCM may be used as an alternative to enhance CCR8 expression in Tregs." (PMID 38231448, 2024).
cancer (continued). "Previous studies have indicated efficacy correlation of CCR8+ Treg cells and CXCL13+ Tex cells with immunotherapy in multiple cancer types;27,28 we therefore matched the infiltration ratio or TCR clonal expansion of CCR8+ Treg cells and CXCL13+ Tex cells with stratified clinical efficacy." (PMID 38897205, 2024). "The Treg_C5_CCR8 cell cluster showed significant immunosuppressive functionality due to elevated expression of TNFRSF family genes and CCR8, facilitating immune evasion and cancer progression." (PMID 38720887, 2024). "The increased expression level of CCR8, interleukin 2 receptor alpha-chain (IL2RA), and Foxp3 indicate regulatory T cell (Treg) infiltration and contribute to the immunosuppression of T cells against cancer." (PMID 34820403, 2021). "Yet, in another group, only receptors were significantly increased (e.g., PDGFRA and CCR8) suggesting that corresponding ligands, PDGF and CCL1, often overexpressed in cancers, may create a chemokine gradient facilitating recruitment of M-LECP." (PMID 28598999, 2017). "Following this clue, several studies demonstrated that targeted depletion of CCR8+ Tregs with enhanced antibody-dependent cell-mediated cytotoxicity (ADCC) strategy induced potent anticancer response and synergized with anti-PD-1 treatment in several murine cancer models." (PMID 40186298, 2025). "However, there is no clinical evidence of the impact of CCR8+ Tregs on CTL activity in the TME of human cancer patients, which we aimed to evaluate in this study." (PMID 38783281, 2024). "Due to the critical role of Tregs in prevention of auto-immune-related diseases, approaches that specifically deplete intratumoral Tregs or that only partially deplete Tregs, by targeting for example CCR8, OX-40, CCR4 and CD2513,33,35,37,73, may be more feasible for use in cancer patients." (PMID 37089449, 2023). "However, to the best of our knowledge, the impact of CCR8+ Tregs on CTL function in human cancer is not fully understood yet." (PMID 35354899, 2022). "Interestingly and similar to the data obtained from cancer secretomes, CCR8+ Tregs secreted less cytokines than CCR8- Tregs, whereas CCR8+ Teff secrete IL-4, but not IFN-γ and IL-17." (PMID 34025655, 2021). "Thus, the treatment with anti-CCR8 may provide a new option for Treg depletion in cancer immunotherapy without major side effects." (PMID 34885241, 2021).
infection (15 papers, 2010 to 2025). The state of being infected such as from the introduction of a foreign agent such as serum, vaccine, antigenic substance or organism. "For example, it has been shown that about 57% of HIV-1 isolates use cell infection chemokine receptor CCR8, which is expressed on the surface of T-lymphocytes." (PMID 37513727, 2023). "One such MCV protein, MC148, is known to function as an inhibitor of CCR8-mediated chemotaxis, limiting T cell migration into sites of infection." (PMID 31034515, 2019). "In this study, CCR8 also increased at the late infection phase and its expression is correlated significantly with CCR8." (PMID 26070790, 2015). "This analysis was done in triplicate at days 1, 3, 6, 9 and 12 post-infection and confirms the exclusive usage of CCR8 as coreceptor by HIV-2MIC97 and HIV-2MJC97." (PMID 25421818, 2014). "At a population level, CCR5 usage by R5 C-HIV Envs was strongly linked to usage of FPRL1, CCR3 and CCR8 as alternative coreceptors, with the linkages to FPRL1 and CCR3 usage becoming statistically more robust as infection progressed from chronic to advanced stages of disease." (PMID 24041034, 2013). "We therefore tested the ability of SIVsmm envelopes to mediate infection through human CCR2b, CCR3, CCR8, GPR1, GPR15 (BOB), CXCR6 and CXCR4." (PMID 20865163, 2010). "A “skinness” of the CCR8-axis is also inferred from the skin-tropic poxvirus molluscum contagiosum whose CCR8-specific antagonist, MC148, is expressed early during infection and may help to evade anti-viral immunity by inhibiting cutaneous CCR8+ Tconv cells." (PMID 35158783, 2022). "The receptor for CCL1 (CCR8) is expressed on specific subsets of TRM, so this mechanism could be in place to recruit TRM at other regions of the tissue to specific niches of infection." (PMID 34566986, 2021). "However, infection resulted in NK cells and ILC1-like cells gaining expression of CCR8 and CX3CR1 compared to NK cells and ILC1s in uninfected mice." (PMID 31393266, 2019). "At day 12 after infection, culture supernatants were used to infect either a pure population of GHOST-CD4/CCR5 or GHOST-CD4/CXCR4 cells, and a 80:20 mixture of GHOST-CD4/CCR8:GHOST-CD4/CCR5 and GHOST-CD4/CCR8:GHOST-CD4/CXCR4." (PMID 25421818, 2014). "As a result of this expression pattern, and based on the significant proportion of HIV strains able to use CCR8 to enter target cells, we may considerer it as a potential alternative HIV coreceptor in vivo contributing to infection of natural target cells, at least under certain circumstances." (PMID 25421818, 2014). "We conclude that a viral population able to use CCR8 and unable to infect CCR5 or CXCR4-positive cells, may exist in some HIV-2 infected individuals during an undefined time period, in the course of the asymptomatic stage of infection." (PMID 25421818, 2014).
inflammation (3 papers, 2020 to 2025). Aberrant reaction of the microcirculation characterized by movement of fluid and leukocytes from the blood into extravascular tissues. "Liver injury driven by CCL1/CCR8-induced monocyte infiltration-differentiation and HSCs activation cause liver inflammation-fibrosis." (PMID 40486848, 2025).
gastrointestinal tumor (2 papers, 2024). "We further found NOTCH3 levels in gastrointestinal tumor to correlate with markers of Dendritic cell(HLA-DPB1, HLA-DRA, HLA-DPA1, BDCA-4), Tfh(T-bet, STAT4, STAT1, TNF-α), Treg cells (FOXP3, CCR8, STAT5B, TGFβ) and T cell exhaustion (PD-1, CTLA4, LAG3, TIM-3)." (PMID 38906903, 2024).
bacterial infection (1 paper, 2022). "Studies have shown that changes in chemokines and chemokine receptors play an important role in the inflammatory response to AD, in which CCL1 and CCR8 prevent bacterial infection from participating in the demyelination of AD." (PMID 36279395, 2022).
cardiovascular diseases (1 paper, 2022). "In cardiovascular diseases, CCR8 is expressed in endothelial cells and macrophages, which stimulates the migration of endothelial cells." (PMID 36246058, 2022).
immune diseases (1 paper, 2025). "CCR8 expression is closely associated with multiple immune diseases, and high expression is often linked to poor prognosis, suggesting it may be a potential therapeutic target for PBC." (PMID 41142241, 2025).
skeletal diseases (1 paper, 2024). "Targeting CCR8+ Tregs and their products could provide a potential strategy for accelerating bone healing and treating skeletal diseases." (PMID 39509336, 2024).
CCR8 also shares sentences with these, for which no sentence is quoted: allergic rhinitis (2 papers); allergies (2); head and neck cancer (2); head and neck squamous cell carcinoma (2); ANCA-associated vasculitis (1); angiosarcoma (1); atopic asthma (1); colon adenocarcinoma (1); diffuse large B-cell lymphoma (1); endometriosis (1); endotoxemia (1); esophageal squamous cell carcinoma (1); gastric adenocarcinoma (1); gastric tumor (1); glomerulonephritis (1); HIV-1 infection (1); inflammatory bowel disease (1); Lewis Lung Carcinoma (1); lung squamous cell carcinoma (1); mycosis fungoides (1); nicotine addiction (1); Obesity (1); rectum adenocarcinoma (1); squamous cell carcinoma (1); steatosis (1); Stroke (1); T-cell leukemia (1); Thyroid carcinoma (1); triple-negative breast carcinoma (1); ulcer (1).
A further 1 disease shares a sentence with CCR8 in 1 paper.